IL6 (interleukin 6)
Diseases named in the same sentence as IL6 in open-access papers (continued):
Sharing a sentence is not in itself a finding about the gene and the disease.
neurodegenerative disease (continued). "The activation of microglia cells can produce NO, PGE2, TNF-α, IL-1β, and IL-6, which can contribute to the inflammatory reaction in neurodegenerative diseases." (PMID 29267220, 2017). "CEBPD is responsive to many proinflammatory cytokines involved in the pathogenesis of neurodegenerative diseases such as interleukin-1β (IL-1β), interleukin-6 (IL-6), and tumor necrosis factor α (TNFα)." (PMID 26208701, 2016). "Animal models and patients with neurodegenerative diseases had higher levels of IL-6 and CRP, providing evidence that peripheral inflammatory mediators can increase ROS production and also interfere with neurocognitive functions." (PMID 27081392, 2016). "Nevertheless, the role of IL-6 in the pathogenesis of neurodegenerative diseases as well as its physiological role in the CNS is under consideration." (PMID 25841889, 2015). "Neurotoxic potential of IL-6 and IL-8 is very well documented in various neurodegenerative diseases including HAND." (PMID 26270987, 2015). "Interleukin-6 (IL-6) and chemokine ligand 5 (CCL5), also known as RANTES (regulated on activation, normal T cell expressed and secreted), have been implicated in neurodegenerative diseases including PD." (PMID 25587378, 2014). "For instance, microglia can compromise the neurogenic cascade during chronic stress, aging, and neurodegenerative diseases, by their release of proinflammatory cytokines such as IL-1β, IL-6, and TNFα." (PMID 24772353, 2014). "In patients with neurodegenerative disease, the CNS has increased numbers of activated microglia and astrocytes, and elevated pro-inflammatory protein levels, such as IL-6 and TNF-α." (PMID 23382826, 2013). "Different groups have demonstrated that the inflammatory cyclooxygenase-2 (COX-2), inducible nitric oxide synthase (iNOS) and cytokines, such as interleukin (IL)-1β, IL-6 and tumor necrosis factor (TNF)-α, are associated with neurodegenerative diseases." (PMID 22214188, 2012). "For example, HIV-1 infected macrophage and DCs are important suppliers of proinflammatory cytokines, including TNF-α, IL-6 and IL-1β, which are etiologically relevant to HIV-1 associated neurodegenerative diseases (HAND)." (PMID 22693544, 2012). "BBB damage has been seen in many neurodegenerative diseases and animal models of seizure, and studies have shown that pro-inflammatory cytokines including TNF-α, IL-1β, IL-6, and interferon-λ are implicated in the regulation of BBB permeability." (PMID 21777430, 2011). "TNFα and IL-6 are the proinflammation cytokines that are dependent on p38 signaling for their production, which has implications in neurodegenerative diseases." (PMID 21533102, 2011). "Our data further support the involvement of caspase-4 in the activation of various neuroinflammatory markers, including t-tau, VEGF, TGF-β, TNF-α, and IL-6, in response to P. gingivalis-LPS in both SH-SY5Y and HMC3 cells, all of which are associated with neurodegenerative diseases." (PMID 40497980, 2025). "Additionally, diltiazem has been shown to exert anti-inflammatory effects by modulating cytokine production, including IL-10 and IL-6, further supporting its potential role in neurodegenerative disease management." (PMID 41322300, 2025). "The results from this study may also provide insights into other conditions of the CNS which are associated with chronic neuroinflammation and increased TNF-α and IL-6 concentrations including neurodegenerative diseases and neuropsychiatric conditions." (PMID 40012566, 2025). "IL-6 has been studied as a molecule linking IBDs to the development of neurodegenerative diseases." (PMID 38891863, 2024). "The M1 microglia cause the release of various inflammatory markers, including tumor necrosis factor-α (TNF-α) and interleukin-6 (IL-6), which may directly damage the CNS and lead to neurodegenerative diseases." (PMID 38473792, 2024). "Increased levels of IL-6 have been observed in AD, PD, and other neurodegenerative diseases." (PMID 38891863, 2024).
neurodegenerative disease (continued). "Dysregulated IL-6 signaling significantly contributes to the pathogenesis of neurodegenerative diseases (AD, HD, and PD) by promoting neuroinflammation, exacerbating Aβ accumulation and tau pathology in AD, compromising BBB integrity, and impairing neuronal survival and synaptic plasticity." (PMID 39015561, 2024). "Additionally, overexpression of IL-6 is a common factor in the pathogenesis of neurodegenerative diseases." (PMID 37760893, 2023). "Interestingly, both pre- and post-administration of VD resulted in a significant reduction in IL-6 and IL-8 secretion, suggesting a potential anti-inflammatory effect of VD in the context of iron accumulation in neurodegenerative diseases." (PMID 38069206, 2023). "This justify the role of IL-6 in the pathogenesis of neurodegenerative diseases." (PMID 36709339, 2023). "On the other hand, β-sitosterol could inhibit neuroinflammation in neurodegenerative diseases through repressing pro-inflammatory markers, including interleukin-6, inducible nitric oxide, cyclooxygenase-2, and the phosphorylation of nuclear factor kappa B." (PMID 36079924, 2022). "While EVs from both 14 and 21 DIV cultures reduced slightly the secretion of the cytokines IFNγ and IL-1a, only EVs from 14 DIV cultures decreased the levels of IL-6, a cytokine predominantly released in neurodegenerative diseases through EVs in the CNS and involved in astrogliosis." (PMID 35163295, 2022). "Astrocytes may contribute to inflammation by serving as an inducible source of inflammatory cytokines, such as IL1β, TNFα, and IL6; these cytokines have been demonstrated to be involved in neurodegenerative diseases, including ALS pathogenesis." (PMID 36046683, 2022). "The activity of neuroprotective and pro-inflammatory factors, namely, brain-derived neurotrophic factor (BDNF), interleukin-6 (IL-6), and tumor necrosis factor-α (TNFα), involved in the neuronal cell damage in neurodegenerative diseases, were assayed in isolated hypothalamus." (PMID 35889920, 2022). "Thus, the uncontrolled release of inflammatory cytokines, such as TNF-α and IL-6, is a key event for neurodegenerative diseases progression." (PMID 33672866, 2021). "High expression of several proinflammatory cytokines and chemokines, including TNF-alpha, MCP, IL-6, and IL-1, have been found in brain tissues from autopsies of patients with neurodegenerative diseases such as PD and MSA, suggesting that these cytokines are involved in the progression of MSA." (PMID 34900026, 2021). "Additionally, IL-6 expression is upregulated in several neurodegenerative diseases, CNS infections and injury." (PMID 34832914, 2021). "Importantly, increasing with age and in neurodegenerative diseases IL-6 expression was recognized as an accelerator of senescence." (PMID 31598806, 2020). "Therefore, the effective use of IL-6 antagonists, soluble IL-6 receptors provides new treatment strategies for neurodegenerative diseases." (PMID 33328961, 2020). "In addition, we evaluated the effects of platycodigenin on the LPS-induced production of TNF-α, IL-6, IL-1β, and IL-10, which are important in neuroinflammation and neurodegenerative diseases." (PMID 31487775, 2019). "Studies have shown that the activation of microglial cells can be induced by LPS, which produces large amounts of reactive oxygen species (ROS), NO, and proinflammatory cytokines such as IL-6 and TNF-α that damage neurons and ultimately cause neurodegenerative diseases." (PMID 31547327, 2019). "In contrast, the levels of IL-6, IL-1β and TNFα in the blood appear to be elevated in patients with both AD and PD, which is the evidence of systemic inflammation that accompanies both of these neurodegenerative diseases." (PMID 29211044, 2017). "Elevated levels of IL-6, IL-1β and TNFα often found in the blood of both AD and PD patients can be considered as the evidence of systemic inflammation accompanied both of these neurodegenerative diseases." (PMID 29211044, 2017).
neurodegenerative disease (continued). "Interleukin-1β (IL-1β), TNF-α and IL-6 are secreted in reactive astrocytes, which may be a first step in the development of several neurodegenerative diseases." (PMID 26729092, 2015). "For example, the activation of astrocytes results in the production of diverse pro-inflammatory cytokines, such as IL-1β, TNF-α and IL-6, which may be a first step in the development of several neurodegenerative disease." (PMID 26729092, 2015). "IL-6 is a neuroprotective factor in many neurodegenerative diseases." (PMID 25811482, 2015). "Therefore, understanding the relationship between IL-6 and rs2228145 could greatly assist clinicians and exercise professionals in personalizing exercise programs for individuals with neurodegenerative diseases." (PMID 40843259, 2025). "As in other neurodegenerative diseases, neuroinflammation was detected in HD patients as well as in HD animal models like the R6/2 mice, in which pro-inflammatory cytokines such as interleukin 6 (IL-6) and tumor necrosis factor alpha (TNFα) were significantly elevated." (PMID 31208073, 2019). "IL-6 and IL-1β are also documented in supporting SC activation in PNI and other neurodegenerative diseases." (PMID 40160208, 2025). "An exacerbated expression of pro-inflammatory mediators, such as interleukin 6 (IL-6) and tumor necrosis factor alpha (TNF-α), can characterize the neuroinflammation present in this neurodegenerative disease." (PMID 40648018, 2025). "This review considers current evidence supporting a mechanistic link between mCRP/CRP/IL-6 signaling and the amplification of stress and pain sensitivity, contributing to a broader understanding of how systemic inflammation may drive vulnerability to neurodegenerative disease." (PMID 41373439, 2025). "In neurodegenerative diseases, microglia contract their protrusions and migrate toward the site of injury, where they release pro-inflammatory cytokines such as IL-1β, TNF-α, and IL-6." (PMID 38649885, 2024). "NF-κB and MAPKs (JNK, ERK, and p38) signaling pathways are pivotal transcription factors for microglial activation and production of cytokines such as IL-1β, IL-6, and TNF-α in various neurodegenerative diseases." (PMID 39764462, 2024). "Both IL-6 and TNF-α are critical pro-inflammatory cytokines in response to LPS, and are considered to be involved in the patho-mechanisms of neurodegenerative diseases." (PMID 37108458, 2023). "The inflammatory mediators elicited by endotoxin and PA assessed in the study included proinflammatory cytokine IL-6, chemokine MCP-1 (CCL-2), and prostaglandin PGE2, which are all important in the CNS and neurodegenerative diseases." (PMID 37571401, 2023). "Thrombin induces the expression of proinflammatory cytokines such as NO, IL‐1β, IL‐6, and TNF‐α by activating PAR, promoting inflammation, and driving the progression of neurodegenerative diseases." (PMID 37654024, 2023). "Since neuroinflammation is a key contributing factor for neurodegenerative diseases, the high levels of pro-inflammatory cytokines, such as tumor necrosis factor-alpha (TNF-α), interleukin (IL)-1β and IL-6, are found in the brain and CSF of patients." (PMID 34068550, 2021). "The expression of IL‐1β, IL‐6, TNF‐α, and iNOS is harmfully correlated with the development of neurodegenerative diseases." (PMID 33942523, 2021). "Proinflammatory cytokines such as TNFα, IL1β, IL-6, and COX2 play an important role in the pathological process of neurodegenerative diseases." (PMID 32560481, 2020). "The inflammatory IL-6 level is reportedly increased at 14 months; therefore, TSPO would probably be upregulated at the later stage of brain degeneration." (PMID 31707986, 2019). "Cartilage degenerative diseases have an inflammatory component involving increased expression of pro-inflammatory factors such as TNF-α, IL-1β, and IL-6." (PMID 31666429, 2019).
neurodegenerative disease (continued). "For instance, it has been reported that DPSCs express interleukin-8 (IL-8), interleukin-6 (IL-6), and TGF-β via Toll-like receptor (TLR) 4 during neuroinflammation in neurodegenerative diseases." (PMID 29853908, 2018). "These inflammatory mediators, such as TNF-α, IL-1ß, IL-6 and PGE2, play an important role in the pathological process of neurodegenerative diseases." (PMID 28410218, 2017). "In a variety of neurodegenerative diseases, the inflammatory response triggered by xenobiotics, chemicals, beta-amyloids, etc., is driven by inflammatory and pro-inflammatory cytokines and chemokines (TNF-alpha, IL-6, etc.)." (PMID 40332055, 2025). "Interleukin 6 (IL6) signaling is an intriguing target to study in neurodegenerative diseases, where non-canonical IL6 trans-signaling is thought to be the dominant pathological mechanism in the CNS." (PMID 39851451, 2025). "The elevated levels of TNF-α and IL-6 observed in LDDD patients align with previous findings that underscore the role of these cytokines in promoting inflammation, matrix degradation, and pain in degenerative diseases." (PMID 40095903, 2025). "Compound 4b can be considered as a lead compound or candidate in the treatment of neurodegenerative diseases because of its remarkable NO-inhibitory activity, potent inhibition against the release of TNF-α and IL-6 and possibly good permeability through the blood–brain barrier." (PMID 40286027, 2025). "Furthermore, increased expression of proinflammatory cytokines such as IL-6, IL-1β, and TNFα that we detected in IFNγ treated SPG11 iMGL, was also described for iPSC-derived microglia from patients with other neurodegenerative diseases, including PD and ALS." (PMID 38305941, 2024). "The accumulation of visceral fat secretes free fatty acids (FFA), interleukin-6 (IL-6), tumor necrosis factor-alpha (TNF-α) and angiotensinogen into the venous circulation, promoting the formation of heterotopic lipid deposition and degenerative diseases." (PMID 36978933, 2023). "The BBB is responsible for protecting the central nervous system (CNS) from the peripheral immune system; however, in many neurodegenerative diseases, such as AD, the integrity of the BBB is compromised by cytokines released by inflammation in the CNS, including TNF-α, IL-6, and IL-1β." (PMID 37323140, 2023). "Our findings demonstrate that microglia responses to IL-6 and IFN-α are highly stimulus-specific, wide-ranging and give rise to divergent phenotypes that modulate microglia responses in neuroinflammatory and neurodegenerative diseases." (PMID 35429976, 2022). "We chose to measure changes in the mRNA expression of interleukin-1β (IL-1β), tumor necrosis factor-α (TNF-α), Fas, interleukin-6 (IL-6), leukemia inhibitory factor (LIF), and interferon γ (IFN-γ) based on their potential involvement in neurodegenerative diseases." (PMID 33628191, 2021). "After determining the effects of FMU200 on cell viability ROS production and mitochondrial function, we evaluated proinflammatory cytokines, such as IL-6 and TNF-α, which are thought to be involved in mediating neuroinflammation and inducing neuronal death in various neurodegenerative diseases." (PMID 33918172, 2021). "OA is not entirely a degenerative disease, being partly an inflammatory condition involving the actions of IL-1β, IL-6, and nitrotyrosine." (PMID 34855756, 2021). "Moreover, the increased growth of Streptococcus would raise the levels of IL-6 and TNF-α, and induce neurodegenerative diseases by inducing neuroinflammation." (PMID 31646147, 2019). "Several studies have shown that aging is accompanied by an increase in the production of pro-inflammatory cytokines, such as IL-6, IL-1β, and TNF-α, which promote chronic inflammation in the elderly and favor the onset and progression of degenerative diseases that are common in this period." (PMID 29232896, 2017).
neurodegenerative disease (continued). "It is becoming increasingly apparent that OA is not simply a degenerative disease, but a multifactorial inflammatory disease involving a host of inflammatory mediators, including IL-1β, IL-6 and NO." (PMID 26083352, 2015). "The role of estradiol is not fully understood, but studies have shown that estradiol plays an important role in neurodegenerative diseases in an anti-inflammatory fashion, since estradiol can upregulate the synthesis and secretion of inflammatory factors, e.g., TNFα, CXCL-8, IL-8, and IL-6." (PMID 35370702, 2022). "Neuroregulatory cytokines such as interleukin-6 (IL-6), ciliary neurotrophic factor (CNTF), leukemia inhibitory factor (LIF), cardiotrophin-1 and cardiotrophin-2 (CT-1 and CT-2), oncostatin-M and neuropoietin are useful in the treatment of neurodegenerative diseases and trauma." (PMID 35833035, 2022). "It is hypothesized that total blockage of the IL-6 production is not beneficial in the treatment of neurodegenerative diseases." (PMID 33918172, 2021). "Although IL-6 elevation would not likely be specific to HD compared to other neurodegenerative diseases, the advent of an effective, dependable salivary biomarker would meet the urgent need for a less invasive means of identifying and monitoring HD disease progression." (PMID 32887270, 2020). "The inflammatory mediators, such as interleukin-1β (IL-1β), interleukin-6 (IL-6), tumor necrosis factor-α (TNF-α), chemokines and oxygen free radicals are assumed to stimulate signaling pathways in a pathological cascade to result in neurodegenerative diseases." (PMID 22607609, 2012). "Strength training for 6-12 weeks did not alter plasma IL-1β, IL-2, IL-6 and TNF-α concentration in healthy elderly adults and patients with chronic-degenerative diseases, while 12 weeks of resistance training decreased muscle TNF-α mRNA in frail elderly individuals." (PMID 33936044, 2021).